LOXL3 (lysyl oxidase like 3)
Diseases named in the same sentence as LOXL3 in open-access papers (continued):
Sharing a sentence is not in itself a finding about the gene and the disease.
glioblastoma (5 papers, 2021 to 2026). The most malignant astrocytic tumor (WHO grade IV). "LOXL1 correlations were detected in LGG with IDH mutation (IDHmut), LOXL3 correlations in LGG with IDH wild type (IDHwt) and strong LOX correlations in glioblastoma (GBM) were found." (PMID 36076905, 2022). "In silico analysis has shown that glioblastoma was among tumors with the highest LOXL3 expression levels." (PMID 34360836, 2021). "Significant correlations of LOXL3 expression with genes coding for tubulins were observed in the mesenchymal subtype in the TCGA RNA-seq dataset of glioblastoma (GBM)." (PMID 34360836, 2021). "To investigate the impact of the LOX family on glioblastoma, we analyzed the expression of LOX family members (LOX, LOXL1, LOXL2, LOXL3, and LOXL4) in normal human astrocytes (Heb) and glioblastoma cell lines (T98G and LN-229)." (PMID 40270974, 2025).
liver cancer (5 papers, 2020 to 2025). An epithelial or non-epithelial malignant neoplasm that arises from the liver. "Importantly, LOXL3 deficiency sensitized liver cancer cells to low-dose Oxaliplatin treatment, with reduced toxicity and increased tumor-killing efficacy." (PMID 37253718, 2023). "In the search for potential drugs targeting LOX and LOXL3 in liver cancer, 30 compounds were identified." (PMID 41250755, 2025). "In both S704D-Loxl3 knock-in mice and transplanted tumor models with S704A-LOXL3, LOXL3 was found to be an important counterpart to low-dose Oxaliplatin for the treatment of liver cancer." (PMID 37253718, 2023). "Exploring the upstream signaling that contributes to LOXL3 mitochondrial localization is beneficial for developing a combination strategy with Oxaliplatin to treat liver cancer." (PMID 37253718, 2023). "Unexpectedly, we observed that mitochondrial lipid peroxidation, but not the total cytosolic ROS, was substantially upregulated by LOXL3 depletion after stimulation of liver cancer cells with Oxaliplatin." (PMID 37253718, 2023). "To explore the association between the LOX family and chemotherapy, we depleted LOX family members individually in these two cell lines and observed LOXL3 depletion sensitized liver cancer cells to chemotherapeutic drugs." (PMID 37253718, 2023). "While the functions of other LOX family members in the liver cancer have been elucidated, those of LOXL3 in liver cancer require further comprehensive research." (PMID 37253718, 2023). "Although LOXL3 has been studied in different types of cancer, studies on its roles in liver cancer are limited." (PMID 35311155, 2022). "In terms of drug resistance, further studies have revealed that LOXL3 promotes chemoresistance in liver cancer by stabilizing dihydroorotate dehydrogenase (DHODH) through activation of the intramitochondrial adenylate kinase 2 (AK2)-LOXL3-DHODH pathway, thereby inhibiting mitochondrial ferroptosis." (PMID 41250755, 2025). "And the oncogenic role of LOXL3 in liver cancer was further supported by TCGA-LIHC cohort." (PMID 37253718, 2023). "LOXL3 depletion significantly sensitizes liver cancer cells to Oxaliplatin by inducing ferroptosis." (PMID 37253718, 2023). "However, studies on the roles of LOLX1 and LOXL3 in liver cancer are limited." (PMID 35311155, 2022). "To further investigate the clinical relevance of AK2-mediated phosphorylation of LOXL3 and DHODH proteins in liver cancer, we first mined the TCGA-LIHC cohort and showed LOXL3 mRNA was upregulated in tumor tissues." (PMID 37253718, 2023). "Moreover, the lysyl-oxidase (LOX) family protein LOXL3 attenuates the ubiquitination of DHODH, in turn inducing the accumulation of DHODH proteins in liver cancer." (PMID 40715045, 2025). "Similarly, while the role of LOXL3 in gastric cancer, colorectal cancer, PDAC, and ovarian cancer has been reported, its significance in liver cancer awaits further investigation." (PMID 33371259, 2020). "Here the authors report chemotherapy induces the phosphorylation of Lysyl oxidase-like 3, which in turn stabilizes dihydroorotate dehydrogenase (DHODH) and that DHODH inhibitor sensitizes tumor cells to oxaliplatin treatment by inducing ferroptosis in liver cancer." (PMID 37253718, 2023).
cleft palate (4 papers, 2015 to 2025). Cleft palate is a fissure type embryopathy that affects the soft and hard palate to varying degrees. "In our previous study, we proposed that the loss of Loxl3 resulted in the decrease in collagen cross-links and collagen content, which lead to delayed palatal shelf elevation, thus resulting in cleft palate." (PMID 40429955, 2025). "Our previous study showed that the loss of LOXL3 resulted in a severe cleft palate and spinal deformity." (PMID 27645581, 2016). "Loss of Loxl3 causes delayed palatal shelf elevation, which in turn resulted in cleft palate." (PMID 40429955, 2025). "Therefore, we theorized that there exists a causal link between cleft palate and perinatal death in our LOXL3 knockout mice." (PMID 26307084, 2015). "Moreover, the loss of LOXL3 resulted in severe craniofacial (cleft palate and shortened mandible) and spinal defects." (PMID 26307084, 2015). "We believe that the mechanism of Loxl3 affecting cleft palate can be studied to help Stickler patients and other patients with cleft palate in clinical practice." (PMID 40429955, 2025). "Exploring the relationship between Loxl3 and cleft palate may be helpful for the clinical research of targeted drugs for the treatment of cleft palate." (PMID 40429955, 2025). "We have not fully elucidated the mechanism by which Loxl3 causes cleft palate, and not elucidated in detail the reasons for other genetic alterations caused by Loxl3 deletion." (PMID 40429955, 2025). "In our study, a significant decrease in collagen-links from the lack of LOXL3 caused cleft palate and spinal deformity, while no obvious difference was observed in the elastin cross-links in the palate and spine." (PMID 26307084, 2015). "In addition to cleft palate, most of the LOXL3 knockout mice also showed a spinal deformity, specifically an abnormal backward bending of the vertebral column." (PMID 26307084, 2015). "Moreover, a missense variant of LOXL3 (c.1843A>T, p.Ile615Phe) was associated with non-syndromic cleft palate, due to lack of catalytic activity of LOXL3 enzyme, with impaired collagen fiber assembly in palatal mesenchyme." (PMID 31340433, 2019). "We showed that the decreased collagen cross-links in the palate and spine induced by the lack of LOXL3 resulted in cleft palates and spinal deformities." (PMID 27645581, 2016).
cutaneous melanoma (4 papers, 2018 to 2024). A primary melanoma arising from atypical melanocytes in the skin. "In addition, in 469 samples of skin cutaneous melanomas from the TCGA, a positive correlation was found for LOXL3 gene expression with both SNAI1 and PRRX1 expression (R = 0.4 and R = 0.45, respectively), as well as for PRRX1 with SNAI1 expression (R = 0.45)." (PMID 35267510, 2022). "The differential expression analyses perfomed using GEPIA2 revealed a significantly higher mRNA expression level for LOXL3 and NES in cutaneous melanomas, both with and without confirmed BRAF mutations, compared to normal skin samples." (PMID 39273022, 2024).
lung fibrosis (4 papers, 2018 to 2022). "Furthermore, these findings extended to LOXL3, which previously had only been linked to lung fibrosis." (PMID 30536539, 2019). "Recently, both LOXL2 and LOXL3 were identified to be crucial for fibroblast-to-myofibroblast transition in in vitro models of lung fibrosis." (PMID 29966587, 2018). "Selective LOXL2/LOXL3 inhibition reduces fibrosis and improves lung function in an in vivo model of lung fibrosis driven by TGF-β." (PMID 29966587, 2018). "The relevance of LOXL2/LOXL3-selective inhibition was demonstrated in a TGF-β-driven rat model of lung fibrosis." (PMID 29966587, 2018). "In addition, they also found increased expression of Loxl2, Loxl3, and Loxl4 in whole lung tissue from pulmonary fibrosis mouse models using gene expression assays at day 14 post-bleomycin." (PMID 34395518, 2021). "In ex vivo and animal models of lung fibrosis, dual inhibition of lysyl oxidase-like (LOXL) 2 and LOXL3 was sufficient to normalise collagen fibrillogenesis, reduce tissue stiffness, and improve lung function in vivo." (PMID 29966587, 2018).
ovarian carcinoma (4 papers, 2018 to 2025). A malignant neoplasm originating from the surface ovarian epithelium. "Complete trypsin peptide or complete trypsinphosphopeptide testing revealed that ovarian cancer-specific proteins include the LOXL3 protein." (PMID 41250755, 2025). "LOXL3 expression was also detected in various kinds of tumors, such as myeloproliferative neoplasms and ovarian carcinoma (primary tumor, metastasis, and peritoneum and pleura effusions)." (PMID 31340433, 2019). "Therefore, higher LOXL3 expression was a predictive indicator of poor clinical prognosis in patients with ovarian carcinoma." (PMID 33058284, 2020). "LOXL3 peptide was detected in the plasma of ovarian cancer patients." (PMID 31340433, 2019). "No investigation has evaluated the function of LOXL3 in ovarian carcinoma." (PMID 33058284, 2020).
colorectal cancer (3 papers, 2021 to 2025). A primary or metastatic malignant neoplasm that affects the colon or rectum. "In summary, in colorectal cancer, high expression of LOXL3 is an important indicator of poor prognosis." (PMID 41250755, 2025). "On the other hand, desflurane enhanced colorectal cancer malignancy via the miR-34a/lysyl oxidase-like 3 axis." (PMID 33673181, 2021). "In cancer, upregulation of LOXL3 has been detected in several tumor types such as gastric, breast, ovarian, and colorectal carcinomas and myeloproliferative tumors." (PMID 34360836, 2021).
fibrosis (3 papers, 2018 to 2023). the formation of excess fibrous connective tissue in an organ or tissue in a reparative or reactive process. "Correspondingly, the use of LOXL2/LOXL3 inhibitor can reduce collagen oxidation and collagen crosslinking, which represents an innovative therapeutic approach for the treatment of fibrosis." (PMID 36968277, 2023).
hepatocellular carcinoma (3 papers, 2022 to 2025). A malignant tumor that arises from hepatocytes. "In another study on hepatocellular carcinoma, LOXL3 was first reported to link with immune infiltrates." (PMID 36159969, 2022). "LOXL3 could augment the process of EMT via enhancing the expression of Snail 1 in hepatocellular carcinoma." (PMID 36324258, 2022).
metastatic melanoma (3 papers, 2018 to 2024). A melanoma that has spread from its primary site to another anatomic site. "LOXL3 expression is thus associated with both primary and metastatic melanomas, and considerably upregulated compared to other LOX family members frequently associated with cancer, such as LOX and LOXL2." (PMID 29229995, 2018). "When analyzing differential expression using GEPIA2, we have found a significantly higher expression for LOXL3 and NES in cutaneous metastatic melanoma, both in BRAF+ and BRAF– tumors, compared to normal skin samples." (PMID 39273022, 2024).
pancreatic ductal adenocarcinoma (3 papers, 2019 to 2022). An infiltrating adenocarcinoma that arises from the epithelial cells of the pancreas. "In pancreatic ductal adenocarcinoma cells, LOXL3 physically interacted with SNAIL to promote proliferation." (PMID 34307505, 2021).
liver fibrosis (2 papers, 2019 to 2024). "Upon LOXL2/LOXL3 inhibition, liver fibrosis was reduced during CCl4 stimulus and STZ‐high fat diet induced NASH." (PMID 30536539, 2019). "LOX proteins (LOX, LOXL1, LOXL2, LOXL3, and LOXL4) are extracellular copper‐dependent enzymes and have been identified as potential therapeutic targets in liver fibrosis." (PMID 38853023, 2024). "Although the CCl4 model recapitulates some of the histological features of liver fibrosis, it was important to determine whether LOXL2/LOXL3 enzymatic functions were also important for crosslink formation in a more physiologically relevant model." (PMID 30536539, 2019).
osteoarthritis (2 papers, 2019 to 2022). A noninflammatory degenerative joint disease occurring chiefly in older persons, characterized by degeneration of the articular cartilage, hypertrophy of bone at the margins and changes in the synovial membrane. "The results have also suggested that LOXL3 plays a significant role in the pathogenesis of leptin-associated osteoarthritis." (PMID 35035830, 2022). "LOXL3 has stimulated apoptosis while inhibited autophagy in chondrocytes; hence LOXL3 is a prominent target for treating osteoarthritis." (PMID 35035830, 2022). "mRNA of LOXL3 was increased in osteoarthritis models which were directly related to leptin concentration in SF." (PMID 35035830, 2022). "Firstly, it was noted that during RT-PCR there is an overexpression of LOXL3 in osteoarthritis patients." (PMID 35035830, 2022). "We conclude that an increase in leptin in rats who were suffering from osteoarthritis have increased the LOXL3 expressions." (PMID 35035830, 2022). "A strong relation was found between the mRNA level of LOXL3 and leptin SF in cartilage in samples from the rat model of osteoarthritis." (PMID 35035830, 2022). "A rat model of osteoarthritis induced by anterior cruciate ligament transection further confirmed the higher expression of Loxl3 in affected cartilage." (PMID 31340433, 2019). "LOXL3 can be found in snails where it lowers the rate of E-cadherin in the development of cancer, to produce the autophagy of chondrocytes in osteoarthritis and to perform a crucial role during the control of integrin signal process for accurate position and anchoring of myofibers." (PMID 35035830, 2022). "The presence of LOXL3 in human tissues has hinted about their role in craniofacial cartilage maturation but is highly expressed in the damaged cartilage of patients suffering from osteoarthritis." (PMID 35035830, 2022). "LOXL3 was one of the genes upregulated in an affected cartilage microarray study of osteoarthritis." (PMID 31340433, 2019). "Upregulation of Loxl3 with leptin treatment of primary chondrocytes from affected rat knees with increased apoptosis and concomitant suppression of autophagy corroborated LOXL3 involvement in osteoarthritis and point to it as a potential therapeutic target in this disease." (PMID 31340433, 2019). "Hence LOXL3 is a probable therapeutic target for treating osteoarthritis." (PMID 35035830, 2022).
adolescent idiopathic scoliosis (1 paper, 2011). A scoliosis with no known cause arising in adolescent. "We hypothesized that common polymorphisms in the five human lysyl oxidase genes (LOX, LOXL1, LOXL2, LOXL3, and LOXL4) may be associated with the phenotype of adolescent idiopathic scoliosis." (PMID 21740577, 2011).
astrocytomas (1 paper, 2022). "LOXL1, LOXL2, LOXL3, and LOXL4 expression levels were also found to increase progressively in astrocytomas from grades 2 to 4, proving highest in GBM, and significantly higher relative to non-neoplastic brain tissue." (PMID 36076905, 2022). "Interestingly, there was a progressive increase in CTNNB1, which codes for β-catenin, according to astrocytoma malignancy grade, and its expression correlated significantly with LOXL1 and LOXL3 expression in both LGG-IDHmut and LGG-IDHwt." (PMID 36076905, 2022). "The progressive gene expression connectivity among LOX, LOXL1, and LOXL3 and matrisome-related genes from LGG-IDHmut, LGG-IDHwt, and through to GBM, reinforce the impact of ECM components contributing for matrix stiffness on the malignant progression and prognosis of astrocytoma." (PMID 36076905, 2022). "Gene expression analysis by quantitative real-time PCR (RT-qPCR) for LOX, LOXL1, LOXL2, LOXL3, and LOXL4 showed increased expression levels in astrocytoma samples compared to non-neoplastic (NN) samples." (PMID 36076905, 2022).
autoimmune disease (1 paper, 2021). A disorder resulting from loss of function or tissue destruction of an organ or multiple organs, arising from humoral or cellular immune responses of the individual to their own tissue constituents. "Eleven proteins (increased: ATP5B, CALML5, COLEC11, FCGBP, PLEK, PLXND1; decreased: APOB, ATP8B1, FAM20C, LOXL3, TIMD4) were significantly altered in bvFTD with autoimmune disease compared to those without autoimmune disease." (PMID 34539672, 2021).
brain tumors (1 paper, 2021). "We sought to further understand the function of LOXL3 in brain tumors." (PMID 34360836, 2021). "Interestingly, GBM, the most frequent and malignant type of brain tumor in adults, was among the top 10 tumors presenting LOXL3 overexpression." (PMID 34360836, 2021).
chondrodysplasia (1 paper, 2015). "LOXL3 knockout mice, which was different from COL2A1 and COL11A1 gene mutant mice, presented with spinal deformity but no dwarfism characteristic of chondrodysplasia." (PMID 26307084, 2015).
diabetes (1 paper, 2022). "Further studies are needed to confirm the function of LOXs, especially LOXL3, in the occurrence and development of periodontal diseases induced by diabetes." (PMID 36134856, 2022). "This shows that LOXL3 could be used as an indicator for the early diagnosis of periodontal diseases induced by diabetes." (PMID 36134856, 2022). "After 9 weeks, LOXL3 expression in diabetic rats showed a slight increase throughout the PDL, but the difference was not statistically significant (control group: MD=0.0556+0.0035; diabetes group: MD=0.0551±0.0067; p>0.05)." (PMID 36134856, 2022).
diffuse large B-cell lymphoma (1 paper, 2025). "Notably, the mutation frequency of LOXL3 is highest in uterine corpus endometrial carcinoma, whereas the frequency of deep deletions is highest in diffuse large B-cell lymphoma." (PMID 41250755, 2025).
ductal breast carcinoma (1 paper, 2022). "Finally, we present clinical evidence that collectively invading cancer cells at the invasive front of ductal breast carcinoma upregulate LOXL3." (PMID 35292774, 2022).
endometrioid ovarian carcinoma (1 paper, 2020). "When considering endometrioid ovarian carcinoma patients, the mRNA expression levels of LOX, LOXL1, LOXL2, LOXL3, and LOXL4 demonstrated no relation with OS or PFS." (PMID 33058284, 2020).
exfoliation syndrome (1 paper, 2025). An autosomal dominant disorder caused by mutations in the LOXL1 gene, encoding lysyl oxidase homolog 1. "LOXL3 is of special interest given that LOXL1, a related lysyl oxidase, is the well-known genetic risk factor for exfoliation syndrome and XFG, with a single polymorphism accounting for the majority of cases." (PMID 41042282, 2025).
hypertension (1 paper, 2019). The presence of chronic increased pressure in the systemic arterial system. "Interestingly, such LOXL3 response to hypertension was strongly influenced by TH1 lymphocytes, suggesting a differential LOXL3 induction according to immune background." (PMID 31340433, 2019).
idiopathic pulmonary fibrosis (1 paper, 2019). Idiopathic pulmonary fibrosis (IPF) is a nonneoplastic pulmonary disease that is characterized by the formation of scar tissue within the lungs in the absence of any known cause. "Additionally, LOXL3 has been involved in idiopathic pulmonary fibrosis (IPF), a chronic disease characterized by uncontrolled and excessive accumulation of ECM and consequent severe lung dysfunction." (PMID 31340433, 2019).
keloid (1 paper, 2021). An irregularly shaped, elevated mark on the skin caused by deposits of excessive amounts of collagen during wound healing. "In addition to collagen-degrading enzymes, we examined the gene-expression levels of collagen-cross-linking enzymes, such as LOX, LOXL-1, LOXL-2 and LOXL-3, finding that they were substantially upregulated in keloid dermal fibroblasts relative to either normal or hypertrophic dermal fibroblasts." (PMID 33672186, 2021).